CD4 (CD4 molecule)
Diseases named in the same sentence as CD4 in open-access papers (continued):
Sharing a sentence is not in itself a finding about the gene and the disease.
colorectal cancer (continued). "Importantly, our data indicated that an antibody neutralizing B7x augmented the response to HDAC inhibitor in the colorectal cancer xenograft model and the lung metastasis model by increasing the ratios of both CD4-positive and CD8-positive T cells." (PMID 32934224, 2020). "Here, we focused on understanding how PFRs might influence CD4+ T-cells to the oncofetal antigen 5T4, which is up-regulated in a number of epithelial-derived cancers including colorectal cancer (CRC)." (PMID 31619516, 2019). "It was reported that BBR could downregulate the phosphorylation levels of JAKs in colorectal cancer and CD4+ T cells." (PMID 30894513, 2019). "A high CD4+/CD8+ ratio has been previously evaluated in different types of cancer and was found to be associated with a good outcome in cervical squamous cell carcinoma and a poor outcome in colorectal cancer." (PMID 28817839, 2017). "In support of a mathematical modeling analysis that reported a correlation between IL-35 and tumors, we demonstrate that elevated IL-35 level in CRC patients is coincident with an increase in Treg cells and it was mainly expressed in CD4+ T cells in human colorectal cancer and adjacent tissues." (PMID 27682874, 2016). "IL-35 mainly expressed in CD4+ T cells in human colorectal cancer tumors and adjacent tissues." (PMID 27682874, 2016). "Presented genes, especially ADAM17, MMP9, EphA2, TIMP1, ICAM 11, and CD4, may be used as prognostic markers of advanced stages of colorectal cancer, contributing to the development of new lines of therapy focused on reducing metastasis of the primary tumor." (PMID 27110571, 2016). "In comparison, lymphocytic infiltration, predominantly CD4+ or CD8+ T cells, in the primary tumor is recognized as an anti-tumor immune response, and a prominent infiltration is associated with improved survival in colorectal cancer." (PMID 25406793, 2014). "Furthermore, tumour tissue selective infiltration of CD4+ T helper cells in colorectal cancer has been demonstrated." (PMID 23349906, 2013). "In 4 colorectal cancer patients sufficient numbers of highly purified CD4+CD25high Treg cells were isolated from peripheral blood by flow cytometric cell sorting before and after vaccination to analyze their inhibitory function in comparison to Treg cells from healthy controls (n = 4)." (PMID 22276195, 2012). "Moreover, after IL-2 treatment of colorectal cancer patients (after treatment), Treg cells had equal suppressive function on conventional CD4+CD25− T-cell proliferation when compared to Treg cells isolated before start of therapy (light grey bar, p<0.001)." (PMID 22276195, 2012). "However, an interesting finding was the difference between colorectal cancer patients and inflammatory bowel disease patients with respect to CD4 expression." (PMID 21864372, 2011). "When the cases were divided by the histological response grade according to the definitions in the Japanese Classification of Colorectal Carcinoma, the density of CD4(+) T cells was 68.7 ± 27.3/field in 27 cases of grade 1 and 89.6 ± 34.0/field in 13 cases of grade 2." (PMID 21575175, 2011). "A significant IgG antibody response to MUC5AC in colorectal carcinoma patients may be indicative of a CD4 helper T cell response." (PMID 16409634, 2006). "The augmented accumulation of CD8 T cells, CD4 T-helper cells, regulatory T cells, and proinflammatory macrophages of the M1 subtype, along with the diminished accumulation of immunosuppressive macrophages of the M2 subtype, are indicative of a more favorable prognosis for colorectal cancer (CRC)." (PMID 38730579, 2024). "Such an approach, in combination with immune checkpoint blockade, could harness colorectal cancer cells as surrogate APCs and generate cancer cells as direct targets for CD4+ T cells and improve the effectiveness of immunotherapy in tumors such as pMMR colorectal cancer." (PMID 37565053, 2023).
colorectal cancer (continued). "Additionally, in vivo studies using adoptive transfer in appropriate mouse models, such as Rag1-/-mice, could elucidate the effect of MCC on CD4+ T cell differentiation in the context of colorectal cancer genesis and development." (PMID 37569317, 2023). "However, as demonstrated in oropharyngeal cancer, colorectal cancer, and other malignancies, circulating CD4+Th subsets may provide potentially significant information regarding the development of malignancy." (PMID 36925914, 2023). "The expression level of KCNJ14 was positively correlated with CD4 + T cells in both COAD (colon adenocarcinoma) and READ (rectum adenocarcinoma) (P = 3.52e-06, COAD; P = 1.26e-05, READ) and negatively associated with CD8 + T cells in colorectal cancer (P = 2.18e-05, COAD; P = 1.58e-02, READ)." (PMID 36100894, 2022). "The results show that except for memory B cells, CD4 memory resting T cells, regulatory T cells, gamma delta T cells, activated dendritic cells, and eosinophils, other subtypes of immune cells’ proportions were remarkably diverse among the three groups in colorectal cancer tissues." (PMID 36551651, 2022). "Moreover, in breast and colorectal cancer, it was found that the CD4+ T cells alone were insufficient for the induction of blood vessel remodeling, while the vascular normalization effect induced by immunotherapy was mediated by the activation of effector CD8+ T cells." (PMID 34439305, 2021). "Interestingly, analysis of the independent human colorectal cancer cohort from TCGA (The Cancer Genome Atlas) database demonstrated that patients with higher level of Bcl6 (in Foxp3+CD4+ cells) showed significantly poorer overall survival compared to those with a lower level." (PMID 32477338, 2020). "Although it is generally accepted that CD4+ T cells may contribute to suppression of tumor growth via TH1 cytokine production, a low CD4+/CD8+ ratio has also been associated with a better prognosis for colorectal cancer patients." (PMID 29499656, 2018). "In colorectal cancer, MMP2, IL1B, IFNG, and CD4 have significant infiltration relationships with many immune cells." (PMID 40868987, 2025). "Silencing AGPAT4 releases lysophosphatidic acid from cancer cells, polarizing macrophages to an M1‐like phenotype, which promotes CD4+ and CD8+ T cell infiltration and activation, influencing colorectal cancer progression." (PMID 40119647, 2025). "In colorectal cancer, SLC2A3 expression positively correlates with CD4+ and CD8+ T-cell infiltration and modulates PD-L1 expression, thereby contributing to immune evasion." (PMID 41268544, 2025). "In colorectal cancer, liver metastasis, CD4+FOXP3+ Tregs, and increased levels of α-smooth muscle actin, HGF, and c-MET indicate potential therapeutic targets for this metastatic form of colorectal cancer." (PMID 40281554, 2025). "In colorectal cancer, the POL&PBRM1 group had more CD4+ memory T cells, and CD8+ T cells (CD8+ naive T cells, CD8+ effector memory T cells, and CD8+ central memory T cells)." (PMID 39218995, 2024). "The higher the Treg and its ratio to CD4+ T and CD8+ T cells, the shorter the OS in patients with colorectal cancer liver metastases." (PMID 38032223, 2024). "Specimens from 267 colorectal cancer cases were analyzed by immunohistochemistry to determine GSDMB expression, CD3+, CD4+, and CD8+ T lymphocytes, CD20+ B lymphocytes, CD68+ macrophages, and S100A8+ immune cells." (PMID 38711020, 2024). "For example, microsatellite instability high (MSI-H) colorectal cancer has a higher concentration of CD8+ cytotoxic and Th1 CD4+ T cells than MSS (microsatellite stable) cancers, contributing to the better prognosis of these cancers." (PMID 37426665, 2023). "In colorectal cancer, the reduction of METTL3 or METTL14 rises cytotoxic tumor-infiltrating CD8+ T cells and stimulates the recruitment of CD4+ and CD8+ effector T cells that suppress tumor growth." (PMID 37236993, 2023).
colorectal cancer (continued). "In our result, there was a better prognosis for patients with ARGscore-low and subtype A, with higher infiltration of activated CD4+, CD8+ T cells, and Tfh, suggesting a potential role of ARG in the development of colorectal cancer." (PMID 36909170, 2023). "Survivin-based vaccine, composed of a pool of three SLPs with eight CD4+ epitopes and six CD8+ epitopes, has shown to activate both CD4+ and CD8+ immune responses in mouse models for colorectal cancer." (PMID 37513965, 2023). "We analysed 12,592 tissue microarray (TMA) spots from 3,545 colorectal cancers sourced from more than 240 institutions in two clinical trials (QUASAR 2 and SCOT) stained for CD4, CD8, CD20, CD68, FoxP3, pan‐cytokeratin, and DAPI by mIF." (PMID 37697694, 2023). "Principal component analysis reduction of RNA profiles in CD4+TIM‐3+ T‐cell and CD4+TIM‐3− T‐cell indicates dysregulation of lncRNA RP11.770J1.4 in colorectal cancer." (PMID 38116063, 2023). "In the context of cancer immunology, CD4 memory T cells play an instrumental role in TME and increased infiltration was detected in colorectal cancer and triple-negative breast cancer." (PMID 35928267, 2022). "Specifically, we isolated epithelial cells, fibroblasts, and four types of TIICs (CD4+, CD8+T cells, DCs, and macrophages) in tumors and four types of PBMCs (CD4+, CD8+T cells, DCs, and monocytes) in peripheral blood from seven colorectal cancer patients." (PMID 36345336, 2022). "It was also found that an increased percentage of activated CD4+CD25+Foxp3− and CD8+CD25+ T cells reduced tumor progression during colorectal cancer development in vivo." (PMID 35265722, 2022). "To investigate the expression profile of SENP7 in tumor-infiltrating T cells, we isolated CD4+ T cells and CD8+ T cells from patient-derived colorectal cancer (CRC) tissue for immunoblot analysis." (PMID 35143421, 2022). "Further, the number of tumor-infiltrating CD4+ and CD8+ T cells in patients with MSI-H colorectal cancer who benefit from pembrolizumab immunotherapy was significantly higher than in the MSS colorectal cancer." (PMID 35774798, 2022). "It has been reported that HDAC inhibitors can alter the subgroup of CD4 and CD8 tumor-infiltrating T cells in colorectal cancer and enhance the effectiveness of immunotherapy in multiple myeloma." (PMID 35912105, 2022). "(A) Representative pictures of T cell infiltration (CD4, CD8, FOXP3) in colorectal cancer (CRC) tissues for VPS9D1-AS1 quantification." (PMID 36458816, 2022). "We then analyzed the infiltration levels of B cells, CD4 T cells, CD8+ T cells, neutrophils, macrophages, and dendritic cells in colorectal cancer." (PMID 35205408, 2022). "Regarding colorectal cancer, tumors with high infiltrate of CD8 and T helper 1 (CD4) type cells had a better prognosis than those with a low infiltrate." (PMID 35311077, 2022). "The accumulation of myeloid-derived suppressor cells necessary to maintain the activation and proliferation of CD4+ and CD8+ T cells was reduced when METTL3 was selectively depleted in colorectal cancer cells." (PMID 36591468, 2022). "Receiver operating characteristic curve analysis to evaluate the use of CD4+ TSCM, CEA, and CA199 in early screening and auxiliary diagnosis of colorectal cancer." (PMID 34327142, 2021). "The median OS, 3-year and 5-year survival rates of colorectal cancer patients in a high density group of CD8+ T cells, CD4+ T cells, or CD4+ GzmB+ T cells were higher than the low-density group respectively." (PMID 34631551, 2021). "To this end, we first quantified host cell mRNA expression and histone acetylation levels following exposure to physiological concentrations of VOR in Jurkat cells, CD4 T cells, and HCT116 cells, a colorectal cancer cell line used in the development of VOR." (PMID 32295913, 2020).
colorectal cancer (continued). "To understand this better, we assessed the relationship between CD3-, CD4- and CD8-expressing cells in a separate cohort of normal colonic epithelium and colorectal cancer by singleplex IHC and multiplex immunofluorescence." (PMID 32684627, 2020). "In colorectal cancers, high expression of CD163 on TAMs was found in TME, resulting in an increased number of CD4+ lymphocytes that contributed to up-regulate the PD-1 expression." (PMID 32756500, 2020). "CD4+ TAI subsets co-expressing inhibitory PD-1 and activating ICOS as well as CD39 and CD69 were detectable in freshly resected colon tumor from MMRd colorectal cancer patients known to express neo-epitopes due to accumulated point-mutations." (PMID 31412943, 2019). "There was one trial that reported that C. versicolor and G. lucidum related natural products had a favorable effect on elevating the levels of CD3, CD4, and CD4/CD8 in colorectal cancer, gastric cancer, and NSCLC, respectively." (PMID 31333449, 2019). "Compared to several other cancer types, including lung, and colorectal cancers, TILs from about a third of RCC patients showed an increased proportion of DP CD4+CD8+ T cells (>5%, reaching 30–50% of T cells in some patients)." (PMID 30534127, 2018). "In another study, autologous DCs, when fused with the allogeneic colorectal carcinoma cell line COLM‐6, induced both CD4+ and CD8+ T cells and CTL responses that break down autologous colorectal carcinoma cells." (PMID 28944998, 2018). "We show that eYFP expression (percentage of eYFP+ cells of CD3+CD4+ cells) gradually increases in tumour-bearing (ID8 ovarian cancer and MC38 colorectal cancer) mice over time." (PMID 28290453, 2017). "Clinical characteristics of colorectal cancer (CRC) patients: T cell clones (Tcc) generated and pre/postoperative values of circulating CD4+ regulatory T cells (Tregs)." (PMID 29375559, 2017). "In vitro study indicated that colorectal cancer cells suppressed IFN-γ expression and increased IL-17a expression in activated CD4+ T cells." (PMID 28147310, 2017). "In colorectal cancer, progression from stage T1 to T4 is reportedly accompanied by a gradual decline in stromal counts of CD3+ cells, which include those that are CD4+ and/or CD8+." (PMID 27441558, 2016). "CXCL16 expression is also strongly correlated with increased tumor infiltration of CD4+ and CD8+ T cells in colorectal cancer, and improved survival in cancer patients." (PMID 27471636, 2016). "As Treg cells with a naïve phenotype were increased in patients with colorectal cancer, particularly post IL-2 treatment, we were interested to assess whether the increase of Treg cells resulted from peripheral expansion or possibly thymic generation of CD4+CD25highFOXP3+ Treg cells." (PMID 22276195, 2012). "Milašienė reported that counts of CD4+T cells, CD8+T cells and NK cells directly correlated with long-term overall survivals of patients with colorectal cancers and gastric cancers of stage III." (PMID 21029461, 2010). "In colorectal cancer, HLA-DRB5 expression levels are significantly correlated with the infiltration of CD8+ T cells, CD4+ T cells, and dendritic cells, implying that tumors in the NSTAS group of our samples might exhibit greater immune cell infiltration." (PMID 40786043, 2025). "In the prevention of inflammation‐driven colorectal cancer, RES suppresses the proinflammatory T‐cell response by reducing Th1 and Th17 cell populations while enhancing the presence of anti‐inflammatory CD4+ FOXP3+ Tregs and CD4+ IL‐10+ cells." (PMID 40502812, 2025). "In the MR analysis pertaining to immune cell characteristics and colorectal cancer, we observed that the count of SNPs integrated into CD25 on CD39+ activated CD4 regulatory T cells (ebi-a-GCST90001940), and CD25 on CD39+ CD4 regulatory T cells (ebi-a-GCST90001935), was <3." (PMID 39612465, 2024).
colorectal cancer (continued). "In a clinical trial on 47 colorectal cancer patients, several immune parameters such as IL‐1, IL‐6, IFN‐γ, CD3 and CD4 were altered after 12 weeks of oral administration of G. lucidum, suggesting that it may be helpful in modulating tumour immunity." (PMID 38451046, 2024). "Moreover, the high expression of ARHGAP4 in colorectal cancer is related to the immune cells such as B cells, CD8+ and CD4+ T cells, macrophages, neutrophils, and dendritic cells." (PMID 38355537, 2024). "We first investigated whether tumor-infiltrating CD4+ T cells express IFN-I by multispectral flow cytometry on head and neck cancer (HNSC) and colorectal cancer (CRC) tissue digests." (PMID 38383773, 2024). "CD4+ T cells specifically induce the expression of mitochondrial TOMM34, and the role of TOMM34 in cancer cell growth suggests its potential in anti-cancer drug development or colorectal cancer diagnosis." (PMID 39185313, 2024). "In addition to validating the high expression of CD200 in endothelial cells in bioletters, flow cytometry also found that epithelial cells and CD4+ T cells also expressed CD200 in three tumors, and fibroblasts in colorectal cancer were highly expressed CD200." (PMID 39120585, 2024). "The GSE116347 dataset consists of CD4+ Treg cells from 12 surgically resected and cryopreserved human colorectal carcinomas or normal colon tissues, classified into Tumor Tregs and Normal Tregs." (PMID 39273290, 2024). "Similarly, T cell memory expression was reduced, B cell memory was increased, CD4+ resident memory T cells and CD8+ resident memory T cells were reduced in colorectal cancer." (PMID 36890467, 2023). "Increasing evidence confirmed that administration with DEX was associated with improved postoperative immunosuppression, as reflected by the increased CD4+:CD8+ ratio and Th1:Th2 ratio, and the results were also confirmed in the patients with colorectal cancer." (PMID 37064099, 2023). "An animals study reported that JK5G could slow the development of colorectal cancer and inhibit inflammatory factors in serum while the spleen became more densely loaded with lymphocytes, such as T, CD3+CD4+ T, and CD3+CD8+ T cells." (PMID 37601658, 2023). "Thus, the cytotoxic CD4 T cells in colorectal cancer are skewed towards a Tr1-like suppressive phenotype in the absence of treatment, while PD1 blockade can convert the pro-tumor Tr1-like cytotoxic CD4 T cells towards a more anti-tumor Th1-like phenotype." (PMID 37654482, 2023). "Ablation studies in colorectal cancer have found that Programmed cell death 1 ligand 1 (PD-L1) expression in target tumor tissues and programmed death 1 (PD-1) expression in specific CD8+ and CD4+T lymphocytes are increased." (PMID 36761748, 2023). "High CD4+/CD8 + ratio has long been thought to be a key indicator of improved prognosis and higher cell immune function, however, there are some controversial opinions in the context of colorectal cancer." (PMID 37189020, 2023). "We recently reported the relapse-free survival (RFS) significance of the combination of CD4+ and forkhead box P3+ (FOXP3) T-cell densities identified by immunohistochemistry in patients with stage I, II, and III colorectal cancer (CRC) who underwent curative resections." (PMID 36253752, 2022). "Importantly, the abnormal overexpression of Mapk14 in colorectal cancer is related to the level of immune infiltration of immune cells (including CD8+ T cells, neutrophils, dendritic cells, B cells, CD4+ T cells, and macrophages)." (PMID 35141222, 2022). "Similarly, treatment of colorectal cancer-bearing mice with anti-CTLA-4 antibodies decreased Foxp3+/CD4+ Treg cells, but increased CD4+ T and CD8+ T cells and the expression levels of pro-inflammatory Th1/M1-related cytokines IFN-γ, IL-1α, IL-2, and IL-12." (PMID 35159059, 2022). "Therefore, NACT enhanced the antitumor immune response by promoting the recruitment of CD4+GzmB+ T cells and CD8+ T cells in colorectal cancer." (PMID 36439457, 2022).